KLF3 (KLF transcription factor 3)
Description:
Binds to the CACCC box of erythroid cell-expressed genes. May play a role in hematopoiesis (By similarity).
Synonyms: BKLF
Tractability: PROTAC: UniProt records ubiquitination sites on it; ubiquitination databases record sites on it.
Gene: Protein-coding gene on chromosome 4 (38,664,032 to 38,701,517, forward strand). Ensembl gene ENSG00000109787.
Subcellular location: Nucleus
Subcellular location (Human Protein Atlas): Nucleoplasm
Gene Ontology:
Molecular function: protein binding; sequence-specific double-stranded DNA binding; DNA-binding transcription factor activity; DNA-binding transcription factor activity, RNA polymerase II-specific; RNA polymerase II cis-regulatory region sequence-specific DNA binding; RNA polymerase II transcription regulatory region sequence-specific DNA binding
Biological process: hemopoiesis; regulation of transcription by RNA polymerase II; cellular response to endothelin; negative regulation of transcription by RNA polymerase II
Cellular component: nucleoplasm; chromatin; nucleus
Genetic constraint (gnomAD): Loss-of-function variants: 6 observed, 25.23 expected, observed/expected ratio (o/e) 0.24, 90% interval 0.13 to 0.47. The upper end of that interval is the gene's LOEUF score, 0.47, which puts it in group 2 of 6, group 1 being the genes least tolerant of losing a copy. Missense variants: 283 observed, 405.67 expected, observed/expected ratio (o/e) 0.7, 90% interval 0.63 to 0.77. Synonymous variants: 131 observed, 159.78 expected, observed/expected ratio (o/e) 0.82, 90% interval 0.71 to 0.95.
Homologues: Orthologues: chimpanzee KLF3 (100% identical), macaque KLF3 (100% identical), rabbit KLF3 (98% identical), guinea pig KLF3 (97% identical), pig KLF3 (96% identical), dog KLF3 (96% identical), rat Klf3 (96% identical), mouse Klf3 (95% identical), tropical clawed frog klf3 (70% identical), zebrafish klf3 (42% identical), Drosophila melanogaster luna (26% identical). Paralogues in human: KLF12 (42% identical), KLF8 (35% identical), KLF5 (30% identical), KLF4 (28% identical), KLF6 (27% identical), KLF7 (26% identical), KLF2 (26% identical), KLF11 (25% identical), KLF1 (23% identical), KLF15 (23% identical), KLF10 (23% identical), KLF17 (21% identical), and 10 more.
Diseases named in the same sentence as KLF3 in open-access papers:
KLF3 is named in the same sentence as 60 diseases in open-access papers, as found by Europe PMC text mining. Sharing a sentence is not in itself a finding about the gene and the disease. The quoted sentences say what the papers report.
lung carcinoma (17 papers, 2019 to 2024). "Bioinformatics analysis showed that KLF3 level was associated with EMT in lung cancer, with lower expression in the cancer tissues less than those in the adjacent ones." (PMID 38560274, 2024). "Loss of KLF3 potentiates lung cancer metastasis and EMT process through controlling the STAT3 pathway." (PMID 35311620, 2022). "To better understand the functional significance of KLF3 in regulating the biological processes of lung cancer cells, we performed loss‐of‐function experiments of KLF3 by transfection with specific siRNA targeting KLF3." (PMID 30485570, 2019). "To explore the molecular mechanism underlying how KLF3 modulates metastasis in lung cancer cells, we further analyzed an online database by gene set enrichment analysis (GSEA)." (PMID 31486564, 2019). "In order to investigate the mechanisms underlying the effect of KLF3 on cell proliferation of lung cancer cells, we examined cell cycle and apoptosis by flow cytometry." (PMID 30485570, 2019). "Of note, the patients with high level of KLF3 were associated with poor overall survival (OS) caused by lung cancer (P = 0.001)." (PMID 30485570, 2019). "Bioinformatics analysis showed that KLF3 level was associated with prognosis by EMT, the epigenetic silencing KLF3 mRNA increased the pro-metastatic miR-182 expression, with the mechanism of lung cancer metastasis dependent on activating STAT3 signaling pathway." (PMID 38560274, 2024). "Sun et al45 found that a low level of KLF3 is associated with the poor prognosis of lung cancer, and KLF3 could alter the epithelial‐mesenchymal transition by controlling STAT3, ultimately affecting metastasis." (PMID 32281273, 2020). "Together, these results suggested that the highly expressed KLF3 may be associated with lung cancer progression." (PMID 30485570, 2019). "Surprisingly, we found that the enrichment of STAT3 target gene sets is associated with reduced KLF3 expression in lung cancer, suggesting that KLF3 may be involved in the STAT3 signaling pathway." (PMID 31486564, 2019). "In lung cancer, KLF3 is deemed an oncogenic factor, and its silencing suppressed cell growth, immigration and invasive capacity, reflecting its role in stomach cancer." (PMID 38305787, 2024). "The KLF3 expression in lung cancer was lower than that in adjacent tissues, which was associated with poor prognosis and TNM stage." (PMID 38560274, 2024). "According to in vitro and in vivo research, KLF3 inhibition accelerates lung cancer EMT and promotes lung cancer metastasis through the STAT3 signalling pathway." (PMID 35345512, 2022). "Silencing KLF3 contributes to lung cancer metastasis and the EMT process by regulating the STAT3 signaling pathway." (PMID 35311620, 2022). "Aberrant expression of KLF3 is related to the occurrence and progress of various tumors, such as acute leukemia, sarcoma, lung cancer, colorectal cancer, and melanoma cancer." (PMID 35311620, 2022). "There was a similar study reported in lung cancer that demonstrated that miR‐326/Sp1/KLF3 regulatory axis is involved in the development of lung cancer." (PMID 35715760, 2022). "Aberrant expression of KLF3 has been detected in several cancers, such as lung cancer, acute leukemia, colorectal cancer, soft tissue sarcoma." (PMID 35311620, 2022). "KLF3 regulatory axis is involved in the development of lung cancer, suggesting a possible target for future lung cancer therapy strategies." (PMID 35627101, 2022). "Recently, the involvement of KLF3 in the progression of cancers, particularly lung cancer, has been partly identified." (PMID 33817265, 2020). "Considering the urgent need to explore novel therapeutic targets for lung cancer metastasis, we determined the potential role of KLF3 in lung cancer metastasis and examined the expression levels of KLF3 in clinical lung cancer tissues in this study." (PMID 31486564, 2019).
lung carcinoma (continued). "To further assess the clinical value of KLF3, we first detected the KLF3 protein expression levels in 56 pairs of human lung cancer tissues and matched normal lung tissues." (PMID 31486564, 2019). "The mRNA and protein levels of KLF3 were also significantly higher in lung cancer cell lines than that in control HBECs, especially in A549 and 95D cells (P < 0.01)." (PMID 30485570, 2019). "More importantly, bioinformatics analysis and in vitro experiments indicated that the role of KLF3 in lung cancer metastasis is dependent on the STAT3 signaling pathway." (PMID 31486564, 2019). "Our data indicated that KLF3 is a key factor in lung cancer metastasis and that KLF3 mediates the induction of EMT to promote lung cancer." (PMID 31486564, 2019). "The results showed that KLF3 was overexpressed in lung cancer tissues compared with that in adjacent normal tissues (P < 0.001)." (PMID 30485570, 2019). "To investigate the promotion of metastasis mediated by KLF3 knockdown, we performed animal experiments to validate the function of KLF3 knockdown in lung cancer." (PMID 31486564, 2019). "Overall, these findings strongly indicated that KLF3 acts as a crucial suppressor of lung cancer by regulating metastasis via STAT3 expression." (PMID 31486564, 2019). "Our data demonstrated that the knockdown‐mediated promotion of tumor metastasis is dependent on the STAT3 signaling pathway and that KLF3 expression is markedly related to lung cancer development in a clinical database." (PMID 31486564, 2019). "To explore the potential role of KLF3 in lung cancer progression, we firstly assessed the expression level of KLF3 in lung cancer tissues." (PMID 30485570, 2019). "Then, we examined the expression of KLF3 in different lung cancer cell lines by real‐time PCR and Western blot." (PMID 30485570, 2019). "In vitro and in vivo experiments also showed that KLF3 silencing promotes lung cancer EMT and enhances lung cancer metastasis." (PMID 31486564, 2019). "Collectively, these data suggest that KLF3 silencing mediates EMT progression and that KLF3 is involved in lung cancer development." (PMID 31486564, 2019). "Considering that KLF3 is related to lung cancer metastasis, we established stable cell lines expressing shRNA‐KLF3 via lentiviral infection." (PMID 31486564, 2019). "In summary, our study provides evidence that miR‐326/Sp1/KLF3 regulatory axis involves in lung cancer cell proliferation, migration and invasion, which provide leads for the further therapy to patients with lung cancer." (PMID 30485570, 2019). "For example, in 2018, KLF3 was demonstrated to participate with miR326 to form a regulatory axis and suppress the progression of lung cancer cells." (PMID 31462890, 2019). "The results showed that Sp1 was upregulated in lung cancer tissues compared with that in the adjacent normal tissues (P < 0.001), which correlated with the expression of KLF3 in lung cancer tissues." (PMID 30485570, 2019). "Forty lung cancer tissues and paired tumour‐adjacent normal tissues were collected from Jiangsu Province Hospital, and the mRNA level of KLF3 was examined by real‐time PCR." (PMID 30485570, 2019). "In summary, these results indicated that KLF3 participated in the regulation of lung cancer cell proliferation, migration and invasion." (PMID 30485570, 2019). "To investigate the role of KLF3 in human lung cancer progression, we first examined KLF3 expression in normal and cancerous human lung tissues by bioinformatics analysis (data were obtained from the Oncomine database)." (PMID 31486564, 2019). "Our findings suggested that the KLF3/STAT3 signaling pathway is a potential therapeutic target for patients with lung cancer." (PMID 31486564, 2019). "To assess the role of KLF3 in lung cancer cell proliferation, we compared changes in cell proliferation between the three groups." (PMID 31486564, 2019).
lung carcinoma (continued). "We found that the messenger RNA (mRNA) expression of KLF3 was markedly downregulated in lung cancer tissues compared to normal tissues." (PMID 31486564, 2019). "The result of IHC indicated that the amount of KLF3 protein in lung cancer tissues was remarkably increased compared to that in normal lung tissues." (PMID 30485570, 2019). "Overall, our data indicated the crucial function of KLF3 in lung cancer metastasis and suggested opportunities to improve the therapy of patients with lung cancer." (PMID 31486564, 2019). "Knockdown of KLF3 inhibited lung cancer cell proliferation, migration and invasion, and induced cell cycle arrest and apoptosis." (PMID 30485570, 2019). "Our data demonstrate that miR‐326/Sp1/KLF3 regulatory axis is involved in the development of lung cancer, which hints the potential target for the further therapeutic strategy against lung cancer." (PMID 30485570, 2019). "Overall, these results indicated that the KLF3/STAT3 signaling axis plays a crucial role in lung cancer metastasis." (PMID 31486564, 2019). "To further evaluate the role of the KLF3/STAT3 signaling pathway in lung cancer metastasis in vivo, we performed a rescue experiment in a mouse model." (PMID 31486564, 2019). "KLF3 was found to regulate lung cancer progression through the interaction with miR-326, and the regulatory axis of miR‐326/Sp1/KLF3 in 2018." (PMID 31462890, 2019). "In accordance with previous studies, we demonstrated that KLF3 expression is downregulated in lung cancer tissues and related to the TNM stage in this study." (PMID 31486564, 2019). "Methylated drugs could modulate miR-182 expression via KLF3 as a potential target strategy for lung cancer." (PMID 38560274, 2024). "In lung cancer, inhibited KLF3 is documented to precipitate EMT and metastasis." (PMID 33728488, 2022). "For instance, KLF3 downregulation inhibited tumorigenesis and the development of lung cancer." (PMID 33817265, 2020). "The results indicated that KLF3 expression was elevated in lung cancer tissues." (PMID 30485570, 2019). "Furthermore, we performed Western blot to evaluate the protein level of KLF3 in lung cancer tissues." (PMID 30485570, 2019). "Clinicopathologic features were compared between these groups, and significantly higher recurrence as well as death rate was observed in lung cancer patients with low miR‐326 and high KLF3 levels, when compared to the high‐miR‐326 group and the low‐KLF3 group (P < 0.05)." (PMID 30485570, 2019). "Similarly, the KLF3 expression was highly upregulated in lung cancer tissues compared to that in the adjacent normal control." (PMID 30485570, 2019). "Together, these results suggest that KLF3 facilitates the proliferation of lung cancer cells and may function as an oncogene during lung cancer progression." (PMID 30485570, 2019). "More importantly, we provided new insights into the KLF3/STAT3 signaling pathway in lung cancer." (PMID 31486564, 2019). "We observed that KLF3 knockdown increased the proportion of cells in the G1 phase and decreased the cells in S phase compared with the control, suggesting that KLF3 could accelerate the cell cycle during lung cancer progression." (PMID 30485570, 2019). "Indeed, the enrichment of genes that mediate EMT in lung cancer tissues with low KLF3 expression levels was observed." (PMID 31486564, 2019). "Moreover, reduced KLF3 expression was found in lung cancer tissues, and KLF3‐mediated metastasis was shown to be dependent on the STAT3 signaling pathway." (PMID 31486564, 2019). "In addition, bioinformatics analysis results showed that KLF3 expression is related to lung cancer epithelial‐mesenchymal transition (EMT)." (PMID 31486564, 2019). "However, little is known about the regulatory mechanism of KLF3 in lung cancer cells." (PMID 30485570, 2019). "We determined whether KLF3 regulates STAT3 expression in lung cancer cells." (PMID 31486564, 2019).
lung carcinoma (continued). "Increased accumulation of KLF3 through regulation of the miR-326/Sp1/KLF3 axis leads to the JAK1/STAT3 and PI2K/AKT signaling pathways activation, thereby facilitating the progression of lung cancer." (PMID 38305787, 2024). "KLF3 and KLF4 inhibit the proliferation, migration, and invasion of lung cancer cells, and induce cell cycle arrest and apoptosis." (PMID 35387557, 2022). "Moreover, NEAT1 could contribute to cell proliferation, apoptosis, and invasion in lung cancer via the miR-1224/Kruppel like factor 3 (KLF3) axis, and promoted autophagy by regulating miR-204/autophagy related 3 (ATG3) and enhanced cell resistance to sorafenib in hepatocellular carcinoma." (PMID 33738254, 2021). "KLF3 expression was negatively correlated with STAT3 and vimentin expression in the clinical lung cancer specimens." (PMID 31486564, 2019). "Furthermore, to investigate whether miR‐326 could regulate Sp1 and KLF3 expression, we transfected miR‐326 mimics into lung cancer cells and real‐time PCR results revealed that overexpression of miR‐326 suppressed the expression of Sp1 and KLF3 in both A549 and 95D cells." (PMID 30485570, 2019). "Similarly, existing studies have proved that KLF3 is an important tumor suppressor gene of lung adenocarcinoma, and KLF3 silencing promotes the EMT process in lung cancer." (PMID 36299590, 2022). "To understand whether KLF3 expression is related to EMT and the STAT3 signaling pathway in patients with lung cancer, we conducted an IHC assay to examine the correlation between KLF3, EMT marker, and STAT3 expression in 56 lung cancer specimens." (PMID 31486564, 2019). "Considering the crucial role of STAT3 in tumor progression and the contribution of KLF3 to the effects of STAT3, we examined whether STAT3 is essential for metastasis‐mediated knockdown of KLF3 in lung cancer cells." (PMID 31486564, 2019). "Applying our models to the TCGA lung cancer dataset, we find that smoking may lead to lung disease through the mediation effect of some specific DNA-methylation sites, including site Cg24480765 in gene RP11-347H15.2 and site Cg22051776 in gene KLF3." (PMID 36299590, 2022). "In this study, we showed that a low Krüppel‐like factor 3 (KLF3) expression level is correlated with a poor prognosis and TNM stages in clinical patients with lung cancer and further demonstrated that KLF3 expression is downregulated in lung cancer tissues compared with adjacent normal samples." (PMID 31486564, 2019). "Furthermore, we also found that the knockdown of KLF3 increased the luciferase activity of the STAT3 gene promoter but not the luciferase activity of the mutant promoter in lung cancer cells." (PMID 31486564, 2019). "Whether Sp1 could affect the expression of KLF3 in lung cancer has never been reported." (PMID 30485570, 2019).
colorectal cancer (14 papers, 2017 to 2025). A primary or metastatic malignant neoplasm that affects the colon or rectum. "Decreased KLF3 is associated with aggressive phenotypes and poor prognosis for colorectal cancer patients." (PMID 35311620, 2022). "Decreased KLF3 is associated with poor prognosis and may work as a promising predictor in colorectal cancer." (PMID 35311620, 2022). "Inversely, loss of KLF3 led to malignant phenotypes and poor prognosis of colorectal cancer." (PMID 33817265, 2020). "Specifically, the association of Fusobacteria with Cldn7 suggests a potential role in tight junction destabilization, while its correlation with Klf3 points to its involvement in WNT/β-catenin pathway dysregulation in colorectal cancer." (PMID 40427657, 2025). "Via motif and core regulatory circuitry analysis, multiple important transcription factors in colorectal cancer were predicted, with PHF19, TBC1D16 and KLF3 having a special role to play in colorectal cancer carcinogenesis." (PMID 38542080, 2024). "Further experiments verify the function of the super enhancers governing PHF19 and TBC1D16 in regulating colorectal cancer tumorigenesis, and KLF3 is identified as an oncogenic transcription factor in colorectal cancer." (PMID 34737287, 2021). "It targets kruppel-like factor 3 (KLF3) and significantly suppresses the migration, invasion, and chemoresistance of colorectal cancer cells, suggesting that miR-365-3p may be a potential tumor suppressor in colorectal cancer." (PMID 40016582, 2025). "KLF3 was considered a novel tumor-promoting transcription factor in colorectal cancer." (PMID 38773440, 2024). "Moreover, studies in humans with colorectal cancer have described an unfavorable prognosis at low expression levels of KLF3." (PMID 37892398, 2023). "Klf3 is a transcription factor that plays a pivotal role in activating WNT1 and WNT/β-catenin signaling pathways, which are key drivers of colorectal cancer progression." (PMID 40427657, 2025).